IGF1 (insulin like growth factor 1)
Diseases named in the same sentence as IGF1 in open-access papers (continued):
Sharing a sentence is not in itself a finding about the gene and the disease.
cerebellar degeneration (4 papers, 2017 to 2025). Degeneration of the cerebellum. "Thus, IGF-1-related autophagy might be a mechanism through which mutant proteins are cleared and cerebellar degeneration is prevented." (PMID 35203722, 2022). "IGF-1 may be involved in the pathogenesis of some neurodevelopmental (RTT), and neurodegenerative diseases (PEHO, INCL, cerebellar degeneration and SSPE)." (PMID 28954393, 2017). "Therefore, first of all, to assess those putative neurotrophic factors that may be useful against neuronal death in our model, we carried out gene and protein analyses of BDNF, IGF1, VEGF-A, and VEGF-B along the period of cerebellar degeneration of PCD mice." (PMID 39859255, 2025).
Cholestatic liver disease (4 papers, 2018 to 2026). "In cholestatic liver diseases, IGF-1 and IGF-BP3 formation is reduced, resulting in an impaired GH/IGF-1 axis." (PMID 34444944, 2021). "A recent study demonstrated that in response to increased IGF1 in a rat model of cholestatic liver disease, the cholangiocytes increased both their proliferation and ECM deposition." (PMID 30109019, 2018).
Clear Cell Renal Cell Carcinoma (4 papers, 2021 to 2026). "We previously reported that soluble αKlotho inhibits the migration of clear cell renal cell carcinoma via suppressing the IGF-1-stimulated PI3K pathway." (PMID 33386992, 2021). "A cell line derived from metastatic clear cell renal cell carcinoma highly expresses IGFBP3 and IGF-1 compared to normal proximal tubule cell, and the autocrine actions of IGF-1 and IGFBP3 promote and inhibit cell proliferation, respectively." (PMID 35370981, 2022).
colon adenocarcinoma (4 papers, 2015 to 2023). "It has been linked to the antiapoptotic effects of the GH/IGF-1 axis, described in some colonic adenocarcinomas, and to the expression of peroxisome proliferator-activated receptor (PPAR) gamma, a tumor suppressor gene." (PMID 37374352, 2023). "The LeRoith group demonstrated that administration of IGF-1 to liver-specific IGF-1-deficient (LID) mice with orthotopically implanted colon adenocarcinoma resulted in increased liver metastasis compared with saline controls." (PMID 26441826, 2015). "Induces apoptosis via Fas pathway and blocks the insulin-like growth factor-I (IGF-1, which has a role in cancer development) receptor in human colon adenocarcinoma H29 cells." (PMID 37215217, 2023).
demyelinating disease (4 papers, 2020 to 2025). A broad group of disorders that affect the myelin sheaths that cover the neurons. "IGF-1 has also been targeted as a potential treatment for demyelinating disorders such as MS." (PMID 33669242, 2021). "Thus, despite the ability of IGF-1 to promote the survival of cells from the OL lineage and to enhance oligodendrogenesis under physiological conditions, results from IGF-1-based treatments in demyelinating disorders are mixed." (PMID 33669242, 2021).
disc degeneration (4 papers, 2009 to 2025). "Therefore, genetic or pharmacological modulation of IGF-1/PI3K/CREB/CA12 activity may be a promising therapeutic approach to degenerative disc disease and a novel model for research focusing on IVDD and endplate degeneration." (PMID 33178705, 2020). "Of note, vitamin D can protect disc degeneration and increase TGF-β and insulin -like growth factor - 1 (IGF-1), which are great benefit to IDD repair." (PMID 40727644, 2025).
endometritis (4 papers, 2013 to 2024). An acute or chronic, usually bacterial infectious process affecting the endometrium. "In particular, low serum concentrations of insulin-like growth factor-1 (IGF-1) are associated with a risk of approximately 4-fold higher of developing cytological endometritis." (PMID 36139263, 2022). "Additionally, a low IGF-1 serum concentration and a body condition score of less than 2.75 few weeks before calving were found to be associated with cytological endometritis." (PMID 36139263, 2022). "In this study the leptin concentrations were high in both metritis and clinical endometritis cows whereas IGF-1 concentrations were lower in other cow groups." (PMID 24209779, 2013). "In the present study, concentrations of IGF-1 in normal and subclinical endometritis cows remained high, whereas in cows with clinical endometritis and metritis concentrations of IGF-1 were low." (PMID 24209779, 2013). "Cows with metritis and clinical endometritis almost always had higher adipokines and lower metabolic hormone levels than subclinical endometritis and normal cows at any time-point during the study period, except for insulin and IGF-1." (PMID 24209779, 2013). "The present study demonstrated that circulating adipokines, insulin, and IGF-1 differed in cows with metritis, clinical endometritis or subclinical endometritis, in cows with persistent postpartum uterine inflammation and in cows with low versus high body condition." (PMID 24209779, 2013). "Furthermore, serum leptin, TNF-alpha, IL-1beta and IL-6 were higher in cows with subclinical endometritis compared to normal cows (P < 0.05), and insulin and IGF-1 concentrations were lower in cows with metritis or clinical endometritis." (PMID 24209779, 2013). "The expression of inflammatory cytokines like the tumor necrosis factor-α (TNF-α), Toll-like receptor (TLR) 4, interleukins (IL), insulin-like growth factor-1 (IGF-1), and IGF-binding protein-2 (IGF-BP-2) were reported to be differentially expressed in the uterine of cows affected with endometritis." (PMID 33477832, 2021).
erectile dysfunction (4 papers, 2016 to 2023). Persistent or recurrent inability to achieve or to maintain an erection during sexual activity. "Previous reports suggest that the growth hormone-IGF1 axis is involved in normal penile development and impotence." (PMID 37656189, 2023). "Gene transfer of IGFBP-3 shRNA could improve erectile function via the restoration of cavernous IGF-1 bioavailability and an increase of cavernous cGMP concentration in the pathogenesis of erectile dysfunction in streptozotocin-induced diabetic rats." (PMID 27136480, 2016). "Here we provide two lines of evidence that gene transfer of IGFBP-3 shRNA could improve erectile function via the restoration of cavernous IGF-1 bioavailability and an increase of cavernous cGMP concentration in the pathogenesis of erectile dysfunction in STZ-induced diabetic rats." (PMID 27136480, 2016).
gastrinomas (4 papers, 2017 to 2024). "In gastrinomas, high levels of IGF-1 and its receptor (IGF-1R) were associated with tumor development, progression and aggressiveness." (PMID 39199391, 2024).
glomerulonephritis (4 papers, 2013 to 2023). A renal disorder characterized by damage in the glomeruli. "Further diseases linked to PPROM were nephritis or glomerulonephritis (ACE, COL4A3, COL4A4, IGF1, NOS2, REN, TNF)." (PMID 25264875, 2014). "Histopathological analysis revealed that causes of death in MuGHRKO mice were essentially unchanged, with similar rates of cancer and glomerulonephritis compared to controls, potentially reflecting the lack of alteration in IGF-1 levels when the GHR gene is disrupted in muscle." (PMID 26233957, 2015).
gout (4 papers, 2018 to 2024). A condition characterized by painful swelling of the joints, which is caused by deposition of urate crystals. "IGF1R is one of the loci associated with both urate levels and gout susceptibility in GWAS to date, and IGF-1-IGF-1R signaling is implicated in urate control." (PMID 38347000, 2024). "MR Corge estimates consistently showed that increased serum IGF1 levels could lead to increased height while increased serum urate levels could elevate the risk of gout." (PMID 39513749, 2024). "In contrast, elevated circulating IGF-1 concentrations were reported in patients with gout and insulin resistance." (PMID 38347000, 2024). "Methods and Findings: The Survivorship Promotion In Reducing IGF-1 Trial (SPIRIT) was a parallel three-arm randomized controlled trial of overweight/obese adult cancer survivors without gout at a single center in Maryland, United States." (PMID 34444833, 2021).
head and neck squamous cell carcinoma (4 papers, 2015 to 2023). A squamous cell carcinoma that arises from any of the following anatomic sites: lip and oral cavity, nasal cavity, paranasal sinuses, pharynx, larynx, and salivary glands. "Moreover, no alterations in IGF-1 mRNA levels are found in head and neck squamous cell carcinoma (HNSCC)." (PMID 28143425, 2017).
Hyperhidrosis (4 papers, 2017 to 2023). Abnormal excessive perspiration (sweating) despite the lack of appropriate stimuli like hot and humid weather. "The resulting excessive GH and insulin-like growth factor 1 (IGF-1) lead to physical disfigurements such as front head furrowing, enlargement of facial structures, scalp changes, hyperhidrosis, thickening of the lips, skin wrinkling, and the unrestrained growth of hands and feet." (PMID 36105896, 2022).
hyperphosphatemia (4 papers, 2022 to 2024). Abnormally high level of phosphate in the blood. "Hypercalcemia and hyperphosphatemia in these patients are usually due to the downstream effects of IGF-1 on the Na-Pi cotransporter in the proximal convoluted tubules of the kidneys." (PMID 38137499, 2023). "Interestingly, our data showed that low calcium condition in combination with severe hyperphosphatemia induced a decrease in IGF-1 without modulating IGFR1 mRNA expression." (PMID 37819413, 2024).
hypophosphatemia (4 papers, 2019 to 2024). Lower than normal levels of phosphates in the circulating blood. "Possible explanation for hypophosphatemia is associated with inhibiting the insulin-like growth factor-1 (IGF-1) located in the proximal tubules blocking the phosphate reabsorption, thus resulting in phosphaturia." (PMID 39026680, 2024). "Since IGF-1 is associated with enhanced bone mineralization and upregulation of FGF23 it is assumed that in case IGF-1 is contributing to the regulation of the P homeostasis it would be downregulated in states of hypophosphatemia." (PMID 31329617, 2019).
hypovitaminosis (4 papers, 2019 to 2023). "Both the IGF1 axis and hypovitaminosis D play a role in childhood obesity, either as a cause or a causality." (PMID 37892272, 2023).
idiopathic osteoporosis (4 papers, 2012 to 2023). "The causes of low serum insulin-like growth factor 1 levels in patients with idiopathic osteoporosis remain unclear." (PMID 22613677, 2012). "The findings indicate that for these patients with idiopathic osteoporosis, treatment with cord blood mononuclear cells led to a significant increase in insulin-like growth factor 1 levels, which favors the increase in bone mineral density." (PMID 22613677, 2012). "Part of the structural skeletal abnormalities found in men with primary osteoporosis have also been related to endocrine alterations other than sex hormone action and particularly to impaired insulin-like growth factor 1 (IGF-1) in men with idiopathic osteoporosis." (PMID 34948434, 2021). "Accordingly, not only variation in E action, but also higher IGF-1 levels, have been positively associated with BMD in adult men, and a particular allelic configuration of the IGF-1 gene, leading to reduced IGF-1 levels, was described in a subset of men with idiopathic osteoporosis." (PMID 34948434, 2021).
infantile spasms (4 papers, 2014 to 2025). A rare epilepsy syndrome characterized by onset of epileptic spasms in infants between 2 and 12 months of age, and rarely up to 24 months. "In patients with infantile spasms, low CSF IGF-1 correlated with the severity and length of stress, cortical damage, poor response to therapy and poor cognition." (PMID 28954393, 2017). "ACTH, glucocorticoids and a ketogenic diet can be effective therapies for infantile spasms and they all affect IGF-1 levels." (PMID 28954393, 2017). "In patients with symptomatic infantile spasms, the normalisation of IGF-1 axis, directly or indirectly, may contribute to normal development." (PMID 28954393, 2017).
intracerebral hemorrhage (4 papers, 2017 to 2025). A cerebrovascular disorder characterized by bleeding into one or both cerebral hemispheres including the basal ganglia and the cerebral cortex. "As a marker of the M2 phenotype, IGF-1 was shown to promote CD206 expression in mice with intracerebral hemorrhage, accompanied by elevated levels of anti-inflammation mediators such as IL-10 and transforming growth factor β (TGF-β)." (PMID 37676529, 2023). "In senile rats and traumatic intracerebral hemorrhage models, IGF-1 gene therapy was also found to modulate the proliferation of reactive microglia." (PMID 37676529, 2023). "A previous mice study demonstrated that a reduced IGF-1 level in the early lifespan is associated with increased lifespan, suggesting that there might be detrimental effects of high IGF-1 concentrations in the early lifespan, possibly through reduced intracerebral hemorrhage." (PMID 35832183, 2022).
knee osteoarthritis (4 papers, 2020 to 2025). "Furthermore, the IGF‐1 and IL‐6 changes elicited in our study synergistically align with reducing proinflammatory markers and mitigating cartilage and synovium damage in knee osteoarthritis and cartilage repair animal models." (PMID 41180562, 2025). "However, in a study of patients with knee osteoarthritis, a reduction in pro-inflammatory molecules (MMP-2, IL-1B, IL-6, and IL-8) and an increase in anti-inflammatory molecules (IGF-1 and IL-10) were found at the 1-year follow-up after an SVF injection." (PMID 38391657, 2024).
Lewis lung carcinoma (4 papers, 2010 to 2018). "On the other hand, there has been another report suggesting that miR-223 functions as a potent tumor suppressor of the Lewis lung carcinoma cell line by targeting insulin-like growth factor-1." (PMID 26055874, 2015).
lipid metabolism disorders (4 papers, 2022 to 2025). "However, DDP may also lead to skeletal muscle atrophy by interfering with the insulin-like growth factor-1 (IGF-1)/PI3K/Akt pathway, autophagy, mitochondrial damage, upregulation of proinflammatory factors, calcium homeostasis, and lipid metabolism disorders." (PMID 35096269, 2022).
malignant glioma (4 papers, 2015 to 2025). A grade III or grade IV glioma arising from the central nervous system. "Insulin-like growth factor 1 (IGF1), a neuronal activity-regulated paracrine signaling molecule, mediates olfactory sensory experience-dependent initiation of olfactory bulb high-grade glioma." (PMID 41030446, 2025).
motor neuron disease (4 papers, 2012 to 2023). "Insulin-like growth factor 1 (IGF1) is a potent trophic factor with therapeutic potential for several motor-neuron diseases, including SMA." (PMID 24014320, 2013). "In another study, CSF (but not serum) levels of IGF1 were found to be diminished in individuals with motor neuron disease." (PMID 23497056, 2013).
nasopharyngeal carcinoma (4 papers, 2017 to 2025). A carcinoma arising from the nasopharyngeal epithelium. "In conclusion, this study demonstrates that elevated serum levels of VEGFC, VEGFR-3, and IGF1 are significantly associated with metastasis and poor prognosis in patients with nasopharyngeal carcinoma." (PMID 41333209, 2025). "Therefore, we explored whether osteoclast-derived IGF-1 activates the mTORC1 pathway in nasopharyngeal carcinoma cells." (PMID 38342894, 2024). "The effects of IGF-1 neutralizing antibody, IGF-1R specific inhibitor (NVP-AEW541) and mTORC inhibitor (rapamycin) on nasopharyngeal carcinoma bone metastasis were also explored in animal experiments." (PMID 38342894, 2024). "In summary, these data suggest that tumor cells can induce IGF-1 secretion by osteoclasts and that osteoclast-derived IGF-1 in turn promotes the proliferation of IGF-1R-expressing nasopharyngeal carcinoma cells." (PMID 38342894, 2024). "In our study, we demonstrated that nasopharyngeal carcinoma tumor cells with high IGF1-R expression have a high propensity for bone metastasis, and IGF-1 secreted by osteoclasts promotes the proliferation of tumor cells in the bone marrow through the IGF-1R/AKT/S6 signaling pathway." (PMID 38342894, 2024). "Importantly, immunostaining of bone metastases from clinical nasopharyngeal carcinoma showed that IGF-1R was abundantly expressed in tumor cells and IGF-1 in microenvironmental cells." (PMID 38342894, 2024). "EBV drives NPC metastasis through EBV-encoded LMP1-mediated metabolic reprogramming via activation of IGF1-mTORC2 signaling and nuclear acetylation of the Snail promoter by PDHE1α, LMP1 upregulates calreticulin to induce EMT via the TGF-β/Smad3/NRP1 pathway in nasopharyngeal carcinoma cells." (PMID 35388172, 2022).
Noonan syndrome (4 papers, 2013 to 2025). Noonan Syndrome (NS) is characterized by short stature, typical facial dysmorphism and congenital heart defects. "For example, recognizing that the most common mutation causing Noonan syndrome results in disruption of GH signaling has led some investigators to hypothesize that recombinant IGF-1 will achieve a better outcome than GH." (PMID 24257104, 2013). "In this study, serum IGF‐1 levels in 8 children with Noonan syndrome were in the normal range after rhGH treatment, although they were higher than before treatment." (PMID 37525886, 2023).
oral squamous cell carcinoma (4 papers, 2013 to 2025). "In oral squamous-cell carcinoma, IGFBP3 mRNA expression has been correlated with a more favorable outcome, further supporting its role as an IGF1 inactivator." (PMID 23365645, 2013). "We hypothesized that fibroblast-derived insulin-like growth factor-1 (IGF-1) acts in oral squamous cell carcinoma (OSCC) cells, leading to the non-canonical activation of the HH pathway, maintaining AKT activity and promoting tumor aggressiveness." (PMID 32899449, 2020).
Ovarian cyst (4 papers, 2013 to 2025). The presence of one or more cysts of the ovary. "Additionally, the elevated insulin and insulin-like growth factor-1 levels observed in women with PCOS may contribute to the formation of ovarian cysts." (PMID 40802395, 2025). "Validation of the IGF-1–GPx1–NMD axis and enhancing selenocysteine metabolism in ovarian cyst models may sustainably restore redox homeostasis and improve oocyte quality." (PMID 41009046, 2025). "No ovarian cysts were observed in the RAd-IGF1 group, and the ovaries had similar characteristics to those of the RAd-IGF1 cycling rats, but with a lower number of ovarian follicles and corpora lutea." (PMID 36326686, 2022).
pneumonia (4 papers, 2018 to 2024). An acute, acute and chronic, or chronic inflammation focally or diffusely affecting the lung parenchyma, caused by an infection in one or both of the lungs (by bacteria, viruses, fungi, or mycoplasma.). "Dynamic bioinformatic assay revealed that plasma IGF-1 level is higher in day 1, but lower in day 3 in severe pneumonia-associated ARDS than that in severe pneumonia." (PMID 30018981, 2018).
Prader-Willi syndrome (4 papers, 2014 to 2018). "In patients with Prader-Willi syndrome (PWS) body composition is abnormal and alterations in appetite regulating factors, bone mineral density and insulin-like growth factor-1 (IGF-1) levels have been described." (PMID 29371863, 2018).
respiratory distress syndrome (4 papers, 2013 to 2025). "Research on COVID-19 infection indicates that the pulmonary tissues of persons with respiratory distress syndrome (ARDS) demonstrate elevated levels of insulin-like growth factor 1 (IGF-1), also known as somatomedin C, together with the IGF-1 receptor (IGF-1R)." (PMID 40048451, 2025). "Therefore, this study aims to establish a correlation between plasma levels of IGF1 and TNF-alpha in predicting the risk of developing ROP in premature neonates with respiratory distress syndrome treated with various modalities of respiratory support." (PMID 39194926, 2024).